INS (insulin)
Diseases named in the same sentence as INS in open-access papers (continued):
Sharing a sentence is not in itself a finding about the gene and the disease.
diabetes (continued). "Insulin administration to mice with streptozocin-induced diabetes elicited higher mouse scores in forced swim test, tail suspension test and spontaneous locomotor activity compared to healthy mice." (PMID 35565918, 2022). "Historically, ketogenic diets were used successfully as dietary treatment options for drug-resistant epilepsy, and glycemic management of type 1 diabetes mellitus, before the discovery of insulin." (PMID 36676967, 2022). "β-cells metabolize nutrients to produce energy needed for insulin secretion in response to high glucose, and there is a potential to harness β-cell metabolism for treating diabetes." (PMID 36251711, 2022). "The pancreatic β-cell dysfunction is a focus clinical indication of diabetes by impairing the ability of insulin secretion." (PMID 35313683, 2022). "A total of 1,222 (35.8%), 280 (8.2%), and 1,188 (34.8%) participants were undergoing treatment for diabetes, including oral diabetic medications, insulin, or diet-control, respectively." (PMID 34997924, 2022). "Type 2 diabetes mellitus is characterized by impaired biological effects of insulin and is prevalent in more than 90% of the reported cases." (PMID 36005597, 2022). "It is likely that the reduced expression level of insulin gene transcription factors and incretin receptors explains, at least in part, the molecular mechanism for β-cell failure found in type 2 diabetes mellitus." (PMID 35453568, 2022). "Young people with diabetes also have another unique way of controlling body weight, which is the voluntary reduction/omission of insulin therapy, to induce hyperglycemia, glycosuria, ketonuria and weight loss." (PMID 36528643, 2022). "This stimulation leads to insulin depletion and fetal hypoinsulinemia, contributing to low fetal weight in mothers with severe diabetes." (PMID 35739932, 2022). "The study participants on average seemed to have more advanced type 2 diabetes because of their longer diabetes duration, higher HbA1c level, and higher insulin requirement (0.93 and 0.94 units/kg/day in the linagliptin and empagliflozin group, respectively)." (PMID 36224294, 2022). "Multiple miRs have important roles in normal insulin function and sensitivity, diabetes, and PDAC development." (PMID 34905088, 2022). "In a research by the Diabetes Control and Complications experiment, intense insulin therapy for 6.5 years successfully reduced the incidence of neuropathy by 60%." (PMID 36249656, 2022). "For example, refined grains are known to rapidly increase insulin and glucose levels in the blood, which are known to contribute to insulin resistance (IR), diabetes, and obesity." (PMID 35055797, 2022). "Type 2 diabetes mellitus (T2DM) is a chronic disease characterized by impaired insulin secretion, sensitivity, and hyperglycemia." (PMID 36501700, 2022). "Evidence from the Diabetes Control and Complications Trial suggested that using high doses of insulin was related to weight gain in patients with diabetes." (PMID 36303875, 2022). "Diabetes mellitus is a metabolic disorder characterized by chronic hyperglycemia due to impaired insulin secretion, impaired insulin action, or both." (PMID 35950072, 2022). "Proteinuria, basal insulin dose, HbA1c, and diabetes duration were the remarkable clinical predictors of NH." (PMID 36572938, 2022). "Due to the identified collinearity between arterial hypertension and antihypertensive therapy, between diabetes and insulin therapy, and between antihypertensive and insulin therapy, the latter parameters were excluded from further analysis." (PMID 35602501, 2022). "Diabetes is a chronic disease characterized by an elevated blood sugar level above the normal level due to inadequate secretion of insulin or failure in production of insulin." (PMID 35804638, 2022). "In T1D, the increased fasting blood glucose level, reduced serum insulin level, and reduction of animal weight are essential markers of diabetes." (PMID 35335970, 2022).
diabetes (continued). "It is extremely important fact that C-peptide, produced in equal amounts with insulin and used in assessing endogenous insulin secretion plays a large role in determining the type of diabetes." (PMID 35784568, 2022). "This review is based on a PubMed search using combinations of the terms, «diabetes», «Alzheimer’s disease», «animal model», «mouse», «rat», «insulin» and «brain»." (PMID 36232867, 2022). "Participants were nonpregnant US adults aged 20 years or older who had a diagnosis of diabetes and were currently using insulin." (PMID 36538330, 2022). "In rodent models, diabetes exacerbates age-related muscle loss, insulin-dependent activation pathways regulating protein synthesis are blunted in the muscle tissue of diabetic mice, and decreased muscle size may contribute to muscle atrophy before the onset of overt diabetes." (PMID 36490255, 2022). "The predictive variables from the LR model contained weight, people undergoing procedures, oxygen saturation level, albumin levels, type of diabetes, and use of medications (insulin, metformin, and sulfonylurea)." (PMID 36572938, 2022). "Insulin sensitizers targeting insulin receptors (IR) are a potential drug for the treatment of diabetes." (PMID 36678512, 2022). "Diabetes mellitus is a disease characterized by the inability of the body to produce enough insulin or respond to insulin." (PMID 36072265, 2022). "Reports have shown that CM consumption not only lowers the prevalence of diabetes, but also improves the detrimental effects of hyperglycemic condition, as well as reducing the insulin therapy required by type-1 diabetic patients." (PMID 35888080, 2022). "Changes in glucose induced by insulin injection were more evident and lasting in rats treated with apocynin (diabetes + apocynin group) (P < 0.01)." (PMID 35629342, 2022). "Insulin edema is a rare complication which can present after initiation or intensification of insulin therapy in people with diabetes." (PMID 36180933, 2022). "According to the study results, the majority of patients used more than two medications, had a family history of diabetes, and received both oral medications and insulin therapy." (PMID 36407991, 2022). "A survey using PAID (diabetes related distress) given to 653 diabetes outpatients demonstrated that age, female sex, medication (especially insulin treatment), complications, hospitalization, hypoglycemia, and high HbA1c predicted higher PAID scores." (PMID 35255930, 2022). "At present, diabetes is controlled through drugs, diet control and insulin injections, but there are still shortcomings, such as insulin resistance, the short duration of drug effects and unstable blood glucose maintenance." (PMID 36225311, 2022). "They [only want to manage] the diabetes mellitus [with] oral medication, however [by the protocol] we must use insulin, [requiring] injection [by the patient] on their own in the home (Specialist 1)." (PMID 36584088, 2022). "The attitudes of other people acted as a barrier or a facilitator to being able to manage diabetes with insulin." (PMID 35983585, 2022). "Half of the cohort were non-insulin treated (627/1280, 49%) and 68% (873/1280) had a parent affected with diabetes." (PMID 34789499, 2022). "Both height and weight are measured, along with selected biomarkers, glucose, insulin, and plasma lipids, whereas diabetes history is obtained by self-report." (PMID 36500986, 2022). "The prevalence of diabetes was 23.3% in men and 15.7% in women (p = 0.004), and men with diabetes were more often insulin-dependent compared to women (6.3% for men, 3.1% for women, p = 0.03)." (PMID 35837485, 2022). "In patients with diabetes, insulin and drugs that increase insulin secretion or action on adipose tissue metabolism cause weight gain." (PMID 35896818, 2022). "Diabetes-related eye sight problems were noted as obstacles to insulin treatment, which imposes the assistance of others." (PMID 35854336, 2022).
diabetes (continued). "For both type 1 (T1DM) and type 2 (T2DM) diabetes mellitus, hypoglycemia affects patient safety and glycemic control during insulin therapy (T2DM)." (PMID 36318542, 2022). "Energy metabolism is more active, promoting the occurrence of the glucagon signaling pathway, enabling glucagon to regulate insulin secretion of pancreatic β cells through the cAMP signaling pathway, and reducing the incidence of diabetes." (PMID 35769162, 2022). "Damage to the endoplasmic reticulum will lead to impaired insulin production and eventually to diabetes." (PMID 35655590, 2022). "People in the upper quartile of HbA1c variability were younger, with a higher prevalence of males, had shorter diabetes duration, a higher prevalence of smokers, and a higher prevalence of insulin use." (PMID 35073913, 2022). "Of these baseline and clinical characteristics, gender (female) (p = 0.03) advancing age (p < 0.01), longer duration with diabetes (p = 0.05) and being on insulin therapy (p < 0.01) showed a statistically significant association with poor glycemic control." (PMID 35524335, 2022). "The high cost of insulin places a significant burden on people with diabetes and their supporters, who seek crowdfunding as a solution to raise funds to purchase insulin." (PMID 35436214, 2022). "Glomerular hyperfiltration, which characterizes early DN and is also present in type 1 diabetes mellitus, is most likely produced by factors apart from insulin." (PMID 36111327, 2022). "Regarding diabetes mellitus, insulin resistance and excessive insulin secretion activate, which activates IGF-1 receptor signaling, contributed to the development of pancreatic cancer." (PMID 35887596, 2022). "Secondary bile acids, metabolites of gut microbiota, are involved in the regulation of glucose and lipid metabolism, and can also enhance insulin sensitivity and promote fat metabolism, which is closely related to the formation of obesity and diabetes." (PMID 36245535, 2022). "Diabetes or “diabetes mellitus” is a part of metabolic diseases characterized by hyperglycemia determined by poor insulin secretion, insulin action or both." (PMID 35631282, 2022). "Generalized linear model with leptin or insulin as the dependent variable, maternal diabetes as a factor and maternal BMI or birth weight as potential covariates." (PMID 35197933, 2022). "This cross-sectional study uses data from the National Health and Nutrition Examination Survey to evaluate trends in glycemic control and severe hyperglycemia among US patients diagnosed with diabetes using insulin from 1988 to 2020." (PMID 36538330, 2022). "Women with diabetes were 35% more likely to prescribed antidepressants than men and the risks increased with deprivation, extremes of age and treatment with insulin." (PMID 35638365, 2022). "A total of 32 children (15 girls), 6 to 14 years of age, mean HbA1c 7.5% (SD 0.6), 58.1 mmol/mol, (SD 6.5) and mean diabetes duration of 5.9 years (SD 3.29), and on insulin pumps consented to participate in this study." (PMID 35712259, 2022). "Insulin is a hormone that can significantly affect blood glucose levels, and the abnormal regulation of insulin contributes to the pathogenesis of diabetes." (PMID 36589843, 2022). "Measuring the key diabetic hormone insulin also provides important information for the diagnostics and management of diabetes." (PMID 35884911, 2022). "Type 2 diabetes accounts for 90% of all diabetes and is characterized by defective insulin secretion and/or insulin resistance." (PMID 36438755, 2022). "Type 2 diabetes mellitus (T2DM) is a metabolic disease characterized by decreased β-cells insulin secretion and/or insulin resistance, resulting in chronic hyperglycemia (elevated blood glucose levels)." (PMID 35407097, 2022). "Kidney and pancreas transplantation, in selected patients with diabetes, is the best therapy and is the only approach able to free patients from both dialysis and insulin therapy." (PMID 35329847, 2022).
diabetes (continued). "For example, Escherichia coli and Saccharomyces cerevisiae are key organisms used in the production of insulin for treatment of diabetes through the introduction of the human insulin gene into these microbes." (PMID 35522665, 2022). "The limitation is that Slovak legislation allows for starting insulin pump therapy at the earliest after the 6th month of diabetes duration." (PMID 36231246, 2022). "There are also results indicating an increase of insulin levels in experimental diabetes, both in diabetic rats and the CRL110065 beta cell line, caused by both forms of ghrelin." (PMID 35628187, 2022). "Selective inhibition with PARPi can be an advantage in pushing more insulin-producing cells under pathological conditions and delivers a potential for pilot clinical testing for β cell replacement cell therapies for diabetes." (PMID 36513699, 2022). "PA has long been prescribed to patients with diabetes due to improvements in glycemia and insulin sensitivity." (PMID 35745114, 2022). "Compared to BDC-0, BDC-3/4 were older, had a longer history of diabetes, and were more likely to take insulin injections, alpha-glucosidase inhibitors, and medications for hypercholesterolemia and hypertension." (PMID 36387868, 2022). "A total of 13 studies included participants taking diabetes medications, of these, only 1 study included participants taking insulin." (PMID 36083989, 2022). "Insulin prescription was perceived as worse diabetes while management with diet was understood to be a lesser condition." (PMID 35441727, 2022). "Four of the ten evaluated diabetes apps were integrated with a bolus insulin calculator, simplifying the complex task of insulin dose calculation, a very useful function for patients prescribed with insulin." (PMID 36612402, 2022). "In particular, we focused on documenting diabetes status (the duration of T2DM, serum glucose, HbA1c, HOMA-IR, and insulin use), as this is a well-studied risk factor for advanced liver fibrosis." (PMID 36010180, 2022). "The current study also showed that psychological and neurological disorders play a role in diabetes due to the effect of neural signals on insulin secretion." (PMID 36188660, 2022). "Type 2 diabetes (T2D) is a chronic metabolic disease characterized by hyperglycemia, insulin resistance, and/or impaired insulin secretion and accounts for 90% of diabetes cases." (PMID 36497026, 2022). "Clusters were based on sex, family history of diabetes, educational attainment, fasting blood glucose and insulin levels, estimated insulin resistance and β-cell function, systolic and diastolic blood pressure, and BMI." (PMID 36253773, 2022). "LCN2 expression is elevated by agents that promote IR and is reduced by PPARγ agonists thiazolidinediones (TZDs), an important class of insulin sensitizers used in the treatment of diabetes." (PMID 36079831, 2022). "Another image showed parents with an insulin pump painted on their stomach as a gesture of support to their child who has diabetes." (PMID 36141360, 2022). "Regular aerobic and resistance exercise have been demonstrated to improve the metabolic disorders of diabetes and its complications by inducing body composition, glycemic control, insulin sensitivity, and controlling lipid profile." (PMID 35712028, 2022). "This study aimed to determine the risk of clinically significant biochemical hypoglycemia (CSBH) by HbA1c, fasting C-peptide, mean plasma glucose (PG), and insulin dose in pregnant women type 1 diabetes mellitus according to each trimester of the pregnancy." (PMID 35207323, 2022). "This means that the less insulin secreted to regulate blood glucose level, the more likely it is for blood glucose level to predict diabetes and, vice versa." (PMID 35958851, 2022). "Being older, a longer duration of diabetes, insulin use, obesity, inadequate glycemic control, and diabetes-related complications were significant negative predictors of HRQoL." (PMID 35180266, 2022).
diabetes (continued). "Studies have shown that LAB can alleviate diabetes by regulating intestinal microbiota, reducing intestinal leakage, reducing insulin resistance, alleviating oxidative stress, improving insulin secretion and protecting β cells." (PMID 35564086, 2022). "The recent evidence suggested that insulin secretion is reduced by about 50% in patients with type 2 diabetes mellitus (T2DM)." (PMID 35500009, 2022). "There is also a large amount of synergy and antagonism between hormones, such as the synergistic effect between leptin and insulin and the treatment of diabetes by melatonin osteogenic differentiation inhibition." (PMID 36188222, 2022). "TyG is an indicator to identify insulin sensitivity and the degree of reduced insulin sensitivity is more pronounced in people with diabetes than in those with prediabetes." (PMID 35331213, 2022). "GPx1 is involved in regulating insulin synthesis and secretion, insulin sensitivity, glucose and lipid homeostasis and the onset and progression of diabetes." (PMID 36438755, 2022). "Diabetes is an endocrine disorder related to the abnormal activity of insulin secreted by the islets of the pancreas." (PMID 35747025, 2022). "Reduced muscle mass can result in the worsening of insulin sensitivity, which in turn can result in diabetes." (PMID 35836165, 2022). "In particular, it has been shown that when mice lacking the autophagy-related gene Atg7 are fed a high-fat diet, β-cell apoptosis is increased, insulin secretion is decreased, compensatory β-cell hyperplasia is lost, and diabetes is enhanced." (PMID 35625542, 2022). "Regardless of type of diabetes, in the US alone, 150–250 million people are estimated to be living with insulin-requiring diabetes." (PMID 35565875, 2022). "Recent studies have consistently shown that moderate repetitive exercise for 30 minutes or longer at least three times per week for at least eight weeks improves insulin sensitivity in patients with diabetes, obesity, and metabolic syndrome." (PMID 36589857, 2022). "Above all, compared with women, men have higher creatinine levels and lower insulin sensitivity; therefore, the positive correlation between uACR and diabetes is more significant in men." (PMID 36175972, 2022). "Epidemiological studies have focused on the relationship between AD and the most common disorder of the insulin system, namely, “diabetes mellitus (DM)” and brain insulin resistance is considered a risk factor for AD and related neurodegenerative disorders." (PMID 36589543, 2022). "Given the successful “hybrid” treatment (both insulin and metformin) and her family history for diabetes, the Sanger genetic test for the principal forms of MODY was performed, but no mutations were found." (PMID 36294752, 2022). "The people with T2DM had poor diabetes knowledge, and those using insulin also had poor knowledge about the use of insulin." (PMID 36527016, 2022). "For example, to control diabetes, a poly(4-vinyl phenyl boronic acid-co-2-(dimethylamino) ethyl acrylate) nanogel with insulin-loaded silver nanoparticles has already been developed." (PMID 35200478, 2022). "to analyze the psychosocial factors correlated with the behavioral intention of people with Type 2 Diabetes Mellitus (T2DM) towards insulin use." (PMID 36542050, 2022). "Blood insulin, the main hormone that reduces blood glucose in the body, is an important indicator for the diagnosis and typing of diabetes." (PMID 36082072, 2022). "The majority of respondents had poor diabetes knowledge in all subscales; total knowledge of diabetes (96.7%), general knowledge of diabetes (71.7%), and insulin use knowledge (92.3%)." (PMID 36527016, 2022). "In ten years, more than half of individuals with type 2 diabetes mellitus switch from oral monotherapy (usually Metformin) to insulin therapy to control their blood glucose levels." (PMID 35488292, 2022). "These relationships strengthened with the adjustment for age, sex, diabetes type, and type of insulin therapy." (PMID 35323114, 2022).